SCG2 (secretogranin II)
Diseases named in the same sentence as SCG2 in open-access papers (continued):
Sharing a sentence is not in itself a finding about the gene and the disease.
SCG2 also shares sentences with these, for which no sentence is quoted: pheochromocytoma (4 papers); lung adenocarcinoma (2); Alzheimer disease (1); amyotrophic lateral sclerosis (1); atherosclerosis (1); Brain atrophy (1); breast invasive carcinoma (1); carcinoid tumor (1); cholangiocarcinoma (1); colon cancer (1); dementia (1); endometriosis (1); epilepsy (1); head and neck cancer (1); heart failure (1); kidney cancer (1); leiomyoma (1); lung squamous cell carcinoma (1); malignant pheochromocytomas (1); myocardial infarction (1); neurological diseases (1); Parkinson disease (1); pituitary tumor (1); prostate adenocarcinoma (1); rectum adenocarcinoma (1); REM sleep behavior disorder (1); renal carcinoma (1); small cell lung carcinoma (1); somatotroph tumor (1); uterine corpus endometrial carcinoma (1).